PDE3A (phosphodiesterase 3A)
Diseases named in the same sentence as PDE3A in open-access papers (continued):
Sharing a sentence is not in itself a finding about the gene and the disease.
melanoma (3 papers, 2022 to 2025). A malignant, usually aggressive tumor composed of atypical, neoplastic melanocytes. "Using RIP‐qPCR, we further confirmed that YTHDF3 could catch these transcripts except PDE3A in SK‐MEL‐28 melanoma cells." (PMID 36324258, 2022). "While patient stratification might not be necessary in GISTs due to a high co-expression rate, exploring diagnostics approaches could be beneficial for other tumor types, such as soft-tissue sarcomas, melanoma, and ovarian carcinoma, where PDE3A expression is less frequent." (PMID 40527986, 2025). "In univariate Cox proportional hazard regression analysis, 3 of 11 genes (FCGR2A, PDE3A, and EPPK1) were significantly related to the prognosis of patients with melanoma." (PMID 35664780, 2022). "When combined with the results of univariate Cox proportional hazard regression analysis, 3 of 11 genes (FCGR2A, PDE3A, and EPPK1) were related to the prognosis of patients with melanoma." (PMID 35664780, 2022). "To determine pairwise correlations involving MYBL2 expression and three genes (FCGR2A, PDE3A, and EPPK1), we reanalyzed the transcriptome data of melanoma cases from TCGA." (PMID 35664780, 2022). "Importantly, we identified three key genes (FCGR2A, PDE3A, and EPPK1) that were correlated with the survival of melanoma patients." (PMID 35664780, 2022). "In summary, these results revealed that three key genes (FCGR2A, PDE3A, and EPPK1) may be potential prognostic factors in patients with melanoma." (PMID 35664780, 2022). "Importantly, multivariate Cox regression and survival curve analysis revealed that PDE3A and EPPK1 were negatively correlated with melanoma patient survival; however, FCGR2A was positively correlated with patient survival." (PMID 35664780, 2022).
schizophrenia (3 papers, 2007 to 2023). A major psychotic disorder characterized by abnormalities in the perception or expression of reality. "However, there are biologically interesting genes related to brain volumes including PDE3A, previously related to all aspects of thrombosis, SCN8A linked to cerebellar ataxia with mental retardation, and PDE4B which has been associated with schizophrenia." (PMID 17903297, 2007).
asthma (2 papers, 2017 to 2024). "Chelidonium majus relieved OVA-induced asthma in rats by regulating the Alox15, P4ha1, Pla2g16, Pde3a, Nme1, Entpd8 and Adcy9 genes expression to restore the disorders in energy metabolism and inflammation." (PMID 38671520, 2024).
congestive heart failure (2 papers, 2023 to 2024). Failure of the heart to pump a sufficient amount of blood to meet the needs of the body tissues, resulting in tissue congestion and edema. "It was also reported that inhibitors of the encoded protein of PDE3A may be effective in treating congestive heart failure." (PMID 36979891, 2023).
heart failure (2 papers, 2017 to 2025). Inability of the heart to pump blood at an adequate rate to meet tissue metabolic requirements. "Recently, disruption of the interaction of PDE3A and SERCA2a by targeting the interacting domain with peptides reduced mortality in mice with experimentally induced heart failure." (PMID 40497949, 2025).
liposarcoma (2 papers, 2007 to 2025). A usually painless malignant tumor that arises from adipose tissue. "Pleomorphic liposarcomas were selected for the comparison as they contain frequently low PDE3A mRNA and protein expression." (PMID 40527986, 2025). "The results demonstrated that PDE3A mRNA expression is significantly higher in GISTs than in liposarcomas (median relative gene expression: 2.30 vs. 0.03, p < 0.001)." (PMID 40527986, 2025). "In addition, genes involved in receptor activity, signaling and lipid metabolism (some of which have previously been reported in liposarcoma) such as ACAA2, ARSA, DHRS3, PDE3A, and PPARA, were upregulated." (PMID 17359542, 2007).
Obesity (2 papers, 2021 to 2024). Accumulation of substantial excess body fat. "PDE3A plays a critical role in obesity by regulating cAMP levels in adipocytes, affecting their function and metabolism." (PMID 39594522, 2024). "The results revealed that 18 of the DMR genes were associated with addiction and obesity (ADCY3; ADCY9; ATF4; CDK5R1; CHRNB2; GABRD; GABRG3; GNB1; GNB3; GRK5; HDAC4; HDAC9; MAP2K1; PDE11A; PDE2A; PDE3A; PPP1CA; SLC6A3)." (PMID 34389046, 2021).
Alzheimer disease (1 paper, 2024). A progressive, neurodegenerative disease characterized by loss of function and death of nerve cells in several areas of the brain leading to loss of cognitive function such as memory and language. "Although there are a limited number of studies, antidepressant and anxiolytic effects have also been observed with cilostazol, a PDE3A inhibitor that has been shown to reduce the decline of cognitive function in patients with Alzheimer’s disease." (PMID 39065743, 2024).
aortic valve disease (1 paper, 2026). "PDE3A and CDK8 have all been previously linked to cardiovascular disease or physiology, although not specifically to aortic valve disease, whereas the link between MN1 and cardiovascular disease remains largely unexplored." (PMID 41419685, 2026).
atrial fibrillation (1 paper, 2023). A disorder characterized by an electrocardiographic finding of a supraventricular arrhythmia characterized by the replacement of consistent P waves by rapid oscillations or fibrillatory waves that vary in size, shape and timing and are accompanied by an irregular ventricular response. "In GWAS analysis, we found that minor allele A of the intron variant PDE3A rs11613698 was observed to increase the risk of atrial fibrillation in the Chinese population." (PMID 36979891, 2023). "Therefore, mutation of PDE3A may change the expression level of its downstream proteins, and affect the risk of atrial fibrillation by mediating cardiac remodeling." (PMID 36979891, 2023).
autism spectrum disorder (1 paper, 2023). A spectrum of developmental disorders that includes autism, and Asperger syndrome. "We also observed PDEs (which hydrolyzes both cAMP and cGMP) was associated with psychiatric disorders [OR of PDE1A was 1.0836 for autism spectrum disorder; OR of PDE2A was 0.8968 for Tourette syndrome (TS) and 0.9449 for SCZ; and OR of PDE3A was 0.9796 for MDD; P < 0.05]." (PMID 37605207, 2023).
cardiac hypertrophy (1 paper, 2017). "While PDE1C and PDE3A inhibitors attenuate cardiac hypertrophy and PDE3 inhibitors in the short term enhance LV contractility and overall systolic function, prolonged inhibition of PDE3 is detrimental because it promotes apoptosis and hypertrophy of the remaining cardiac myocytes." (PMID 28750036, 2017).
cerebral amyloid angiopathy (1 paper, 2017). "The effect of PDE3A pathway inhibition was studied in the inflammation-induced and cerebral amyloid angiopathy (CAA)-associated mouse models of CMH." (PMID 28583195, 2017).
cerebrovascular disease (1 paper, 2017). "Finally, absence of protection against CMH development in these models does not rule out a potential therapeutic role for PDE3A modulation in mixed cerebrovascular disease." (PMID 28583195, 2017).
cervical cancer (1 paper, 2017). A primary or metastatic malignant neoplasm involving the cervix. "The results showed that the relative expression of PDE3A mRNA in cervical cancer tissues was significantly lower compared with normal cervical tissues." (PMID 28743736, 2017). "The expression of each and all three PDE3A variants sensitized DNMDP-treated cells, suggesting that the expression of PDE3A indeed regulates DNMDP sensitivity in cervical cancer cells." (PMID 28743736, 2017). "We also found that PDE3A expression is decreased in cervical cancer tissues compared with healthy tissues." (PMID 28743736, 2017). "Interestingly, we found that the expression level of PDE3A is lower in cervical cancer tissues compared with healthy control tissues." (PMID 28743736, 2017). "In addition, our observation that PDE3A overexpression induced sensitivity to DNMDP in cervical cancer cells is similar to a recent report." (PMID 28743736, 2017). "There is no obvious difference in the expression of the three PDE3A variants or in how they modulate DNMDP sensitivity in cervical cancer cells." (PMID 28743736, 2017).
COVID-19 (1 paper, 2021). A disease caused by infection with severe acute respiratory syndrome coronavirus 2. "However, PDE3A was nominally associated with COVID-19 positivity (p = 0.019)." (PMID 35222515, 2021). "The significant association between the gene set containing these genes and COVID-19 hospitalization suggests there may be a genetic basis for the previously reported associations between protein levels of PDE3A and IGF-1 with severe COVID-19." (PMID 35222515, 2021). "Further investigation of pQTLs in PDE3A and IGF-1 will be needed to confirm the genetic relationship between these two proteins and COVID-19." (PMID 35222515, 2021).
delirium (1 paper, 2021). A disorder characterized by confusion; inattentiveness; disorientation; illusions; hallucinations; agitation; and in some instances autonomic nervous system overactivity. "Patients with non-delirium (CAM < 5) showed the greatest relative decrease in PDE3A, while patients with delirium (CAM ≥ 5) had mild decrease or moderate increase in PDE3A." (PMID 34456709, 2021).
diabetic neuropathy (1 paper, 2024). A chronic, pathological complication associated with diabetes mellitus, where nerve damages are incurred due to diabetic microvascular injury involving small blood vessels that supply these nerves, resulting in peripheral and/or autonomic nerve dysfunction. "Cilostazol has demonstrated potential as a pharmacological agent for treating both PAD and diabetic neuropathy due to its ability to inhibit phosphodiesterase-3A, promote vasodilation, inhibit platelet aggregation, and increase cAMP levels." (PMID 39846696, 2024).
dilated cardiomyopathy (1 paper, 2021). Cardiomyopathy which is characterized by dilation and contractile dysfunction of the left and right ventricles. "In addition, we assessed PDE3A protein levels in left ventricular tissue samples obtained from patients with dilated cardiomyopathy (DCM) or ischemic cardiomyopathy (ICM)." (PMID 34763298, 2021).
dyspepsia (1 paper, 2020). An uncomfortable, often painful feeling in the stomach, resulting from impaired digestion. "In particular, the expression of PDE3A in the gastrointestinal tissue, cardiovascular system, and brain has been linked with headache, flushing, and dyspepsia associated with the use of PDE5i." (PMID 33536912, 2020).
essential thrombocythemia (1 paper, 2025). A chronic myeloproliferative neoplasm that involves primarily the megakaryocytic lineage. "ANA, an approved drug for treating essential thrombocythemia, shows promise against tumors that express elevated PDE3A levels, as in the case of GIST." (PMID 39930717, 2025). "Anagrelide (ANA) is a phosphodiesterase 3A (PDE3A) inhibitor, commonly prescribed for essential thrombocythemia." (PMID 39930717, 2025).
glioma (1 paper, 2024). A benign or malignant brain and spinal cord tumor that arises from glial cells (astrocytes, oligodendrocytes, ependymal cells). "Next, we tested a panel of commercially available glioma cell lines with variable levels of PDE3A expression for sensitivity to BAY 2666605." (PMID 39166256, 2024).
HELLP syndrome (1 paper, 2025). A life-threatening condition that can potentially complicate pregnancy. "Secondly, while focused on PDE3A as a key downstream effector of IGF2BP3, we acknowledge the emerging significance of apoptotic and autophagic regulators such as BCL-2 and Beclin-1 in preeclampsia and HELLP syndrome." (PMID 40563987, 2025).
Hydrocephalus (1 paper, 2017). Hydrocephalus is an active distension of the ventricular system of the brain resulting from inadequate passage of CSF from its point of production within the cerebral ventricles to its point of absorption into the systemic circulation. "Interestingly, depletion of either, PDE1A or PDE3A using morpholinos causes pronephric cysts, body curvature, and hydrocephalus in zebrafish." (PMID 28750036, 2017).
Infertility (1 paper, 2023). "PDE3A-deficient oocytes exhibit severe cell cycle arrest, which eventually causes infertility in mice." (PMID 36938502, 2023).
Insulin resistance (1 paper, 2021). Increased resistance towards insulin, that is, diminished effectiveness of insulin in reducing blood glucose levels. "It has been observed that PDE3A, PDE3B, PDE4B, PDE4D, and PDE8B in rat islets and in INS-1E cells activate multiple signal pathways critical for pancreatic beta cell function, and their abnormalities are associated with insulin resistance." (PMID 35046895, 2021).
leukemia (1 paper, 2025). A malignant (clonal) hematologic disorder, involving hematopoietic stem cells and characterized by the presence of primitive or atypical myeloid or lymphoid cells in the bone marrow and the blood. "Besides HEL, SLFN12 was also readily detectable in U937 and SET-2 cells, and to a lesser extent in the remaining leukemia lines, whereas PDE3A was below detection levels in K-562, KG-1, U937, OCI-AML-5, and MV-4-11 cells." (PMID 41150877, 2025). "However, most PDE3A-deficient leukemia cell lines that we tested still responded to treatment with BAY 2666605, suggesting a potential PDE3A-compensatory pathway for velcrin sensitivity." (PMID 41150877, 2025). "To examine this hypothesis, we performed co-immunoprecipitation experiments in U937 cells, a leukemia cell line with undetected PDE3A protein expression but high PDE3B expression." (PMID 41150877, 2025). "We also examined protein expression of SLFN12, PDE3A, and PDE3B in a panel of leukemia cell lines and found that HEL cells exhibit readily detectable amounts of all three proteins." (PMID 41150877, 2025). "We provide evidence that even in less sensitive leukemia cell lines, BAY 2666605 remains effective at relatively low doses and enhances Aza antileukemic effects, suggesting that this combinatorial strategy could be particularly beneficial for patients with lower PDE3A and higher PDE3B expression." (PMID 41150877, 2025). "Here, we provide evidence that physiologic levels of PDE3B, even in the absence of PDE3A, can be sufficient for heterotetrameric complex formation with SLFN12 to induce velcrin-mediated antineoplastic effects, further demonstrating a potential role for PDE3B in velcrin sensitivity in leukemia." (PMID 41150877, 2025).
lipoma (1 paper, 2021). A benign, usually painless, well-circumscribed lipomatous tumor composed of adipose tissue. "Similarly, PDE3A, a major cAMP degradation enzyme, is upregulated in lipoma acting synergistically together with the increase MAOA reducing the lipolytic tone in lipoma." (PMID 33235355, 2021).
liver cancer (1 paper, 2019). An epithelial or non-epithelial malignant neoplasm that arises from the liver. "Moreover, YAP appears to be important in sarcomas and YAP controls PDE3A expression in liver cancer cells." (PMID 30956759, 2019).
lung carcinoma (1 paper, 2020). "However, a recently patented specific PDE3A inhibitor compound has been identified (DNMDP) that appears to induce apoptosis in a set of NCI-60 cancer cells, including lung cancer cells, by enhancing the interaction of PDE3A with SLFN12." (PMID 32987632, 2020). "SLFN12 also sensitizes cancer cells, including lung cancer, to PDE3A inhibitors." (PMID 32987632, 2020).
metastatic disease (1 paper, 2025). "Although we observed a statistically significant association between PDE3A expression and both the number of mitoses and the presence of metastatic disease, these results should be interpreted with caution." (PMID 40527986, 2025).
myxoma (1 paper, 2024). A benign soft tissue neoplasm characterized by the presence of spindle and stellate cells, lobulated growth pattern, and myxoid stroma formation. "Utilizing antibodies against PDE3A, Ki67, CD3, CD8, CD68, and CD206, we employed multiplex immunohistochemical staining to investigate the composition of myxoma cells, T cells, and macrophages in each patient." (PMID 39090109, 2024). "One of the most notable findings was significant upregulation of cyclic nucleotide phosphodiesterase (PDE) gene families, including PDE3A, PDE1A, PDE7B, and PDE10A in myxoma cells." (PMID 39090109, 2024). "Immunofluorescence experiments confirmed the presence of a significant number of PDE3A+ cells within myxoma tissues, while they were virtually absent in normal cardiac tissues." (PMID 39090109, 2024). "Myxoma cells derived from myxoma were found to be independent of normal heart tissue and formed a distinct subset in the integrated profile, with high expression of the myxoma cell marker such as PDE3A and the transcription factor SOX9, which regulate cell differentiation." (PMID 39090109, 2024).
pleomorphic liposarcoma (1 paper, 2025). Pleomorphic liposarcoma (PLS), the rarest subtype of liposarcoma (LS), is an aggressive, fast growing tumor located usually in the deep soft tissues of the lower and upper extremities. "Next, we investigated the correlation between PDE3A protein and mRNA expression in GIST and pleomorphic liposarcoma tissues." (PMID 40527986, 2025).
psoriasis (1 paper, 2023). An autoimmune condition characterized by red, well-delineated plaques with silvery scales that are usually on the extensor surfaces and scalp. "In psoriasis, a study evaluated the influence of the SLCO1C1 rs3794271 and PDE3A rs11045392 polymorphisms on anti-TNF response in 130 white patients (from Spain) and showed that patients carrying the C allele obtained a better response (ΔPASI after 3 months) (p = 0.00057)." (PMID 37240048, 2023).
pulmonary hypertension (1 paper, 2020). Increased pressure within the pulmonary circulation due to lung or heart disorder. "We speculate that increased PDE3A and AMPK by NO have implications in the pathobiology of pulmonary hypertension and may provide rationale for the development of novel isoform‐specific therapeutic targets for the treatment of PPHN." (PMID 32914566, 2020).
renal cystic disease (1 paper, 2017). "Indeed we found that administration of desmopressin aggravated the renal cystic disease of Pkd2-/WS25 mice on a Pde3a null background compared desmopressin-treated Pkd2-/WS25 mice on a wild-type background." (PMID 28750036, 2017).
Right ventricular hypertrophy (1 paper, 2024). In this case the right ventricle is more muscular than normal, causing a characteristic boot-shaped (coeur-en-sabot) appearance as seen on anterior- posterior chest x-rays. "Although we found that Pde3b knockout mice show elevated trends in RVH and increased RVSP, Pde3a knockout mice exhibit more severe right ventricular hypertrophy, increased RV mass, and significant elevations in RVSP." (PMID 39435735, 2024).
sarcoma (1 paper, 2019). A usually aggressive malignant neoplasm of the soft tissue or bone. "YAP has been reported to be expressed in 50% of sarcomas and YAP interaction with TFCP2 controls PDE3A expression." (PMID 30956759, 2019).
Tetralogy of Fallot (1 paper, 2024). A congenital cardiac malformation comprising pulmonary stenosis, overriding aorta, ventricular septum defect, and right ventricular hypertrophy. "PDE3A (Phosphodiesterase 3A, 123805) together with PDE4 (Phosphodiesterase 4A, 600129) has been shown to control the intracellular cAMP and cardiac excitation–contraction coupling, which were further confirmed to be associated with Tetralogy of Fallot, validating our prediction." (PMID 39202774, 2024).
Thrombocytopenia (1 paper, 2021). A reduction in the number of circulating thrombocytes. "Importantly, PDE3A inhibitors or PKA activator ameliorates carbamazepine-mediated thrombocytopenia in vivo." (PMID 34658890, 2021).